RNF213 (ring finger protein 213)
Diseases named in the same sentence as RNF213 in open-access papers (continued):
Sharing a sentence is not in itself a finding about the gene and the disease.
Moyamoya disease (continued). "RNF213 p.R4810K was identified as a susceptibility variant for moyamoya disease in Asia and non-moyamoya intracranial artery stenosis/occlusion disease in Japan and Korea recently." (PMID 29165136, 2017). "Many non-p.R4810K rare variants of RNF213 have been identified in white moyamoya disease patients, although the ethnic mutations have not been investigated in this population." (PMID 27736983, 2016). "Following the initial discovery, a genome-wide association study in Japanese patients with moyamoya disease revealed that 95% of familial and 73% of non-familial patients carried the RNF213 p.Arg4810Lys variant, which conferred an odds ratio of 190.8 for the disease." (PMID 40869930, 2025). "Considering the pivotal role of immune imbalance in Moyamoya disease, this mechanism implies that dysregulated RNF213-mediated ubiquitination could impair Treg function and exacerbate vascular inflammation, potentially linking immune modulation to vascular pathology in MMD." (PMID 41480156, 2025). "Understanding the molecular function of RNF213 could provide insights into moyamoya disease." (PMID 37655297, 2023). "However, importantly, several other RNF213 variants were found in non-Asian populations with moyamoya disease." (PMID 35455046, 2022). "Moyamoya disease (MMD) is characterized by progressive stenosis of intracranial arteries in the circle of Willis with unknown etiology even after the identification of a Moyamoya susceptible gene, RNF213." (PMID 30157848, 2018). "In a murine model, however, transgenic mice with RNF213 knockout or the RNF213 point missense mutation p.Arg4828Lys, which corresponds to the human p.Arg4810Lys variant, did not demonstrate the phenotypes mimicking moyamoya disease and other vasculopathies in a normoxic environment." (PMID 35455046, 2022). "We describe an adult-onset case of moyamoya disease with nonfocal TNAs and a prior TIA associated with a rare RNF213 missense variant not previously linked to the disease." (PMID 40682695, 2025). "Although analyses focused on RNF213 p.Arg4810Lys have been the mainstream approach in MMD, it seems increasingly important to accumulate comprehensive phenotype–genotype analyses, considering the potential implications of these moyamoya angiopathy-related genes." (PMID 38592555, 2025).
cerebrovascular disease (24 papers, 2015 to 2025). "Variants in the RNF213 gene are responsible for a spectrum of cerebrovascular disorders, like moyamoya disease type 2 (OMIM #607151), intracranial aneurysms, and AVMs." (PMID 40259928, 2025). "Ubiquitination of LPS is catalyzed by the RING-type ubiquitin ligase RNF213/Mysterin, a distinct E3 ligase linked to Moyamoya disease, a cerebrovascular disorder." (PMID 38517379, 2024). "Since the discovery of the RNF213 gene in 2011, its role in cardiovascular and cerebrovascular diseases has received a lot of attention due to the identification of RNF213 as a susceptibility gene for MMD." (PMID 37655297, 2023). "They revealed that RNF213 played an important role in cerebrovascular diseases caused by viral infections, thus beginning to unveil the link between RNF213 and viruses." (PMID 37655297, 2023). "The RNF213 gene is the major susceptibility factor for Moyamoya Arteriopathy (MA), a progressive cerebrovascular disorder that often leads to brain stroke in adults and children." (PMID 35562882, 2022). "Here, we evaluated the relationship between the East Asian founder variant RNF213 p.R4810K and consequent anatomical variations in the circle of Willis in cerebrovascular disease." (PMID 34335228, 2021). "There is a clear need for further investigations elucidating the functional role of RNF213 to better understand the underlying pathogenesis for cerebrovascular disease." (PMID 32182997, 2020). "This review elaborates on the advances of the associations between RNF213 and different cerebrovascular diseases." (PMID 30671466, 2018). "Different mutation sites of RNF213 are associated with different cerebrovascular diseases, possibly because different mutations affect different functional domains of RNF213." (PMID 30671466, 2018). "RNF213/Mysterin has been identified as a susceptibility gene for moyamoya disease, a cerebrovascular disease characterized by occlusive lesions in the circle of Willis." (PMID 27736983, 2016). "Future large-scale genetic cohort studies should evaluate the risk of RNF213 R4810K on health outcomes of cardio- and cerebrovascular diseases, such as ischemic stroke, hemorrhagic stroke, myocardial infarction, and hypertension." (PMID 26662949, 2016). "Moreover, a Japanese multicenter prospective cohort study investigated the relationship between the RNF213 p.R4810K variant and echocardiographic findings in Japanese patients with cerebrovascular diseases, focusing on preclinical cardiovascular changes." (PMID 40869987, 2025). "We therefore sought to evaluate the relationship between the East Asian founder variant RNF213 p.R4810K, associated with a single nucleotide polymorphism (SNP; rs112735431), and consequent anatomical variations in the circle of Willis in cerebrovascular disease." (PMID 34335228, 2021). "This review summarizes the advances in the associations between RNF213 and different cerebrovascular diseases and highlights that variant diversity of RNF213 may predispose distinct populations to dissimilar cerebrovascular diseases." (PMID 30671466, 2018). "Therefore, RNF213 variant diversity predisposes distinct populations to dissimilar cerebrovascular diseases." (PMID 30671466, 2018). "Various RNF213 genetic mutations related to cerebrovascular disease have been reported." (PMID 30671466, 2018). "In addition to the relationship with the presence of intracranial cerebrovascular disease, RNF213 variant genotypes may also be associated with the disease progression and long-term outcome." (PMID 32182997, 2020). "In addition to point mutations, it has been found that four frameshift mutations in RNF213 are also associated with cerebrovascular disease, with c.1214_1216delGAG and c.11415delC associated with aneurysms and c.1587_1589delCGC and c.12343_12345delAAA associated with MMD." (PMID 30671466, 2018). "Different site mutations in RNF213 may be involved in different cerebrovascular diseases." (PMID 30671466, 2018).
cerebrovascular disease (continued). "Continued research into RNF213’s ATPase, ubiquitin ligase, and oligomerization activities will be crucial for unraveling its role in cerebrovascular diseases, such as MMD and RRV, and for identifying potential therapeutic targets." (PMID 40869987, 2025). "This study represents the largest population-based analysis of RNF213 and NOTCH3 variants in Koreans and provides valuable insights into the genetic epidemiology of cerebrovascular disorders in Koreans." (PMID 40982447, 2025). "This review synthesizes findings from genetic studies, as well as cellular and animal models, to provide a holistic understanding of RNF213’s involvement in cerebrovascular diseases." (PMID 39857601, 2024). "These insights lay the groundwork for future research and underscore the potential of RNF213 in driving personalized approaches to cerebrovascular disease management." (PMID 39857601, 2024). "Not only that of point mutations, frameshift mutations in RNF213 are also associated with aneurysms (c.1214_1216delGAG and c.11415delC), MMD (c.1587_1589delCGC and c.12343_12345delAAA), and cerebrovascular disease (c.1214_1216delGAG and c.11415delC)." (PMID 39857601, 2024). "Ring Finger Protein 213 (RNF213), also known as Mysterin, is the major susceptibility factor for Moyamoya Arteriopathy (MA), a progressive cerebrovascular disorder that often leads to brain stroke in adults and children." (PMID 35562882, 2022). "RNF213, also known as ‘mysterin’, is the major susceptibility gene for Moyamoya disease (MMD), a cerebrovascular disorder characterized by arterial occlusions and abnormal blood vessel generation." (PMID 32573437, 2020). "Our data support a role of sequence variants in PCNT, RNF213 and THSD1 as susceptibility factors for cerebrovascular disease." (PMID 32367296, 2020). "More studies are required to confirm the correlation of RNF213 with various cerebrovascular diseases, thus providing a new target for the prevention and treatment of cerebrovascular diseases." (PMID 30671466, 2018). "The role of RNF213 in cerebrovascular disorders has been recently discovered in stroke genetics." (PMID 39858606, 2025). "Furthermore, ICASO and MMD, both RNF213-related disorders, are progressive cerebrovascular diseases." (PMID 32182997, 2020). "Although many studies have reported associations between RNF213 variants and cerebrovascular disorders, the underlying pathogenic process has not been established." (PMID 32182997, 2020). "However, recent studies have implicated RNF213 p.Arg4810Lys in ICASO, suggesting that even if the variant does not always lead to classical MMD, its presence may contribute to other cerebrovascular disorders." (PMID 40982447, 2025). "For instance, studies on RNF213-related vasculopathy hold the potential for developing treatments for MMD and other cerebrovascular disorders." (PMID 39858606, 2025). "Further investigations of the functional and biological roles of RNF213 will improve our understanding of the pathomechanisms of ICASO and cerebrovascular disease." (PMID 32182997, 2020).
Stroke (21 papers, 2015 to 2025). Sudden impairment of blood flow to a part of the brain due to occlusion or rupture of an artery to the brain. "Similrly, we have identified several of the most common RNF213 gene variants through WES in our stroke patients: RNF213 rs8082521 (c.3544C > A), rs8074015 (c.4139A > G), and rs4890009 (c.4797G > A)." (PMID 41379817, 2025). "In the present study, RNF213 p.Arg4810Lys was a significant risk factor for stroke in 3.3% of strokes in a 1-year prospective cohort from a single Japanese stroke centre." (PMID 39958261, 2025). "This is consistent with our data showing that the RNF213 mutation increased the risk of progression to moyamoya hemispheres, as well as symptomatic stroke." (PMID 39191959, 2025). "First, we examined the association between ECAS and RNF213 p.Arg4810Lys in consecutive cases treated at our stroke centre over a one-year period." (PMID 39958261, 2025). "In conclusion, this prospective observational study is the first to report that RNF213 p.Arg4810Lys is significantly associated with stroke in 3.3% of the general stroke cases." (PMID 39958261, 2025). "We found that RNF213 p.Arg4810Lys was present in 3.3% of the general Japanese stroke cohort and was a significant risk factor for stroke." (PMID 39958261, 2025). "In this study, the RNF213 variant group was substantially younger, had a family history of stroke, and less diabetes mellitus than the RNF213 wild-type group." (PMID 39531151, 2025). "This study explored the clinical significance and association of RNF213 p.Arg4810Lys with stroke subtypes, ECAS, and max-IMT." (PMID 39958261, 2025). "For RNF213 gene variants, the predominant ones identified in all our stroke patients through whole exome sequencing are RNF213 rs8082521 (c.3544C > A), RNF213 rs8074015 (c.4139A > G), and RNF213 rs4890009 (c.4797G > A)." (PMID 41379817, 2025). "Logistic regression analysis adjusted for age and sex showed that RNF213 p.Arg4810Lys was significantly associated with stroke (adjusted odds ratio [aOR], 3.25; 95% confidence interval [CI], 1.46–8.34; P= 0.014)." (PMID 39958261, 2025). "We aimed to elucidate the clinical significance and association of RNF213 p.Arg4810Lys with stroke subtypes, extracranial artery stenosis, and maximum intima-media thickness." (PMID 39958261, 2025). "RNF213 Arg4810Lys was further associated with extracranial arterial stenosis, elevated maximum intima–media thickness in arteries, and increased stroke risk." (PMID 40869185, 2025). "In a meta-analysis involving three Japanese population studies with 46,958 East Asian individuals (17,752 cases and 29,206 controls), RNF213 p.R4810K was associated with increased stroke risk (OR 1.91, 95% CI 1.55–2.36)." (PMID 39857601, 2024). "Among various stroke subtypes, large-artery atherosclerosis, both due to intracranial artery stenosis and extracranial artery stenosis, was most significantly associated with RNF213 p.Arg4810Lys." (PMID 39958261, 2025). "Genetic analysis studies focusing on East Asian-specific gene variants, such as RNF213 p.Arg4810Lys, may identify stroke-associated gene variants unique to populations." (PMID 39958261, 2025). "RNF213 p.Arg4810Lys was significantly associated with stroke." (PMID 39958261, 2025). "In conclusion, RNF213 p.Arg4810Lys increases the risk of stroke." (PMID 39958261, 2025). "Controversy exists over which subtype of stroke is associated with the RNF213 p.Arg4810Lys variant." (PMID 39958261, 2025). "The association of RNF213 p.Arg4810Lys with various stroke subtypes was studied." (PMID 39958261, 2025). "The exact mechanisms by which RNF213 variants lead to vascular abnormalities and increased stroke risk remain unclear." (PMID 39858606, 2025). "Emerging evidence suggests that RNF213 variants may influence stroke risk by precipitating a broader spectrum of vascular conditions, including intracranial artery stenosis (ICAS)." (PMID 39857601, 2024).
Stroke (continued). "Discovery of a pathogenic role of RNF213 gene in ICASO may provide a novel therapeutic target in ICASO with high risk for stroke." (PMID 32182997, 2020). "Therefore, this study aimed to determine the frequency of the RNF213 p.Arg4810Lys variant in the general stroke population, identify the stroke subtypes associated with RNF213 p.Arg4810Lys, and investigate the association between RNF213 p.Arg4810Lys and max-IMT." (PMID 39958261, 2025). "In conclusion, by describing a large group of children carrying predicted deleterious RNF213 variants we prove that this gene is associated with a more severe clinical presentation, characterized by early onset, posterior involvement and higher stroke rates in multiple territories." (PMID 37012328, 2023). "Among different stroke subtypes, MMD and LAA were significantly associated with RNF213 p.Arg4810Lys (aOR, 77.55; 95%CI, 9.56–628.76; P< 0.001, aOR, 14.55; 95% CI, 4.41–48.05; P < 0.001, respectively)." (PMID 39958261, 2025). "Another case of an RNF213 Arg4810Lys carrier developed Herpes simplex virus-1-related infantile encephalitis but also developed stroke and vascular abnormalities." (PMID 40869185, 2025). "This large-scale study highlights the substantial genetic burden of RNF213 and NOTCH3 variants in Koreans, which partially contributes to the high stroke burden in East Asia." (PMID 40982447, 2025). "RNF213 p.Arg4810Lys was significantly associated with concurrent ICAS and ECAS in the Japanese stroke group." (PMID 39958261, 2025). "A cohort of 600 patients with stroke prospectively collected over 1 year was assessed for the presence of RNF213 p.Arg4810Lys." (PMID 39958261, 2025). "Stroke in patients with RNF213 p.Arg4810Lys was characterized by a history of dyslipidaemia (59% versus 36%, P= 0.036) and coronary artery disease (29% versus 13%, P= 0.022)." (PMID 39958261, 2025). "As RNF213 patients are younger than non-RNF213 ones, the possible confounding effect of age was excluded by comparing the angiographic and stroke data only in RNF213 and non-RNF213 patients below 5 years (60 months) of age." (PMID 37012328, 2023). "Both NF1 patients with (possibly) deleterious RNF213 variants, in whom PCA involvement was also seen, were excluded from further analysis of arterial involvement and strokes." (PMID 37012328, 2023). "The specific association between RNF213 gene variants and pediatric MMD and stroke has been described previously, both in children heterozygous or homozygous for the founder East‐Asian p.(Arg4810Lys) variant as well as in children with rare, de novo variants." (PMID 33960657, 2021). "We present a patient with hemorrhagic MMD (RNF213 gene mutation) who developed depression and catatonia over time following MMD-related strokes." (PMID 30564539, 2018). "Among the various subtypes of stroke, LAA was significantly associated with RNF213 p.Arg4810Lys." (PMID 39958261, 2025). "Although RNF213 and NOTCH3 variants show incomplete penetrance, carriers may have an elevated stroke risk when exposed to environmental factors such as smoking, hypercholesterolemia, and a sedentary lifestyle." (PMID 40982447, 2025). "We further examined the proportion of our cohort with ICAS and ECAS, independent of stroke subtype, and analysed the association with RNF213 p.Arg4810Lys." (PMID 39958261, 2025). "This study included 1024 non-MMD subjects (636 ischemic stroke and 388 non-stroke subjects) who underwent genotyping of RNF213 variants and angiographic evaluation." (PMID 32182997, 2020). "The RNF213 p.Arg4810Lys variant (rs112735431, c.14429G > A) was detected in 25% of the individuals (35/139; 35 heterozygotes) who were significantly younger, had a family history of stroke, and had less diabetes mellitus than those without the risk allele." (PMID 39531151, 2025). "Evaluating RNF213 p.Arg4810Lys may help predict the incidence and type of stroke." (PMID 39958261, 2025).
Stroke (continued). "Some investigators have proposed reclassifying ischemic strokes in RNF213 variant carriers—particularly those lacking overt moyamoya vessels—as “stroke of other determined etiology (non-inflammatory arteriopathy)” rather than conventional atherosclerosis under the TOAST classification system." (PMID 40869987, 2025). "Apart from pathogenic or likely pathogenic findings, 41 rare VUS in 325 stroke-related candidate genes were detected in 39 probands, including eight novel variants: ABCA1 p.H1223P, ACTA2 p.N298S, COL5A1 p.P930R, FBN1 p.Q514E, FBN1 p.K1052T, GP1BA p.P437*, RNF213 p.N1631Efs*34, and TSC1 p.P397del." (PMID 36580209, 2023). "RNF213 p.Arg4810Lys has been reported to be associated with LAA, but its detailed association with the stroke subtype has not been elucidated." (PMID 39958261, 2025). "RNF213 p.Arg4810Lys was more common in patients with stroke (3.3%) than in those without stroke (1.1%)." (PMID 39958261, 2025). "Furthermore, cerebral angiogenesis by hypoxia was suppressed in RNF213 knockout mice, which could contribute to MMD, as the suppression of cerebral angiogenesis would decrease oxygen delivery to the brain and impair stroke recovery." (PMID 39857601, 2024).